APOE (apolipoprotein E)
Diseases named in the same sentence as APOE in open-access papers (continued):
Sharing a sentence is not in itself a finding about the gene and the disease.
dementia (continued). "There was a non-significant trend for the association between APOE genotype and dementia to be weaker in those with greater degrees of African admixture." (PMID 21435264, 2011). "Controlling for ethnic identity or admixture did not affect the association between APOE genotype and dementia, suggesting an absence of confounding by population stratification." (PMID 21435264, 2011). "One or more APOE-e4 alleles was associated with dementia in 'white' and 'black' but not 'mixed' groups but neither this, nor the interaction between APOE-e4 and African admixture (PR 0.52, 95% CI 0.13-2.08) were statistically significant." (PMID 21435264, 2011). "Increased levels of ABCA1 and ApoE may be the molecular determinants of cholesterol dyshomeostasis and accompanying dementia observed in AD." (PMID 20843353, 2010). "In addition, changes in LXR/RXR target genes, ABCA1 and ApoE in AD brains as a function of the increasing severity of dementia and neurofibrillary pathology were also observed." (PMID 20843353, 2010). "In those studies, a higher risk of dementia among smokers was found, but only among APOE ε4 non-carriers." (PMID 20515477, 2010). "The study revealed that the effect of stroke on dementia did not seem tobe modified by the presence of the APOE 4 allele." (PMID 29213654, 2010). "Interventions designed to reduce the incidence of stroke may also be effective in reducing the incidence of dementia, particularly in APOE ε4 carriers." (PMID 20576093, 2010). "Based on these findings, we postulate that stroke and APOE may lead to dementia via related mechanisms." (PMID 20576093, 2010). "Odds Ratios for genotypes containing an APOE ε4 allele were increased in the group with a positive family history compared to those without dementia in first degree relatives." (PMID 18416843, 2008). "Significantly increased ORs were found in all genotypes containing the APOE ε4 allele, both for the group with dementia in first degree relatives and for those with a negative family history." (PMID 18416843, 2008). "In patients with dementia in first degree relatives 70.9% (n = 151) had one or two APOE ε4 alleles, compared to 56.4% (n = 84) in patients with no known history of dementia in first degree relatives (p = 0.004)." (PMID 18416843, 2008). "Other studies have found that APOE ɛ 4 modifies dementia outcome in individuals with previous traumatic head injury, suggesting that APOE ɛ 4 plays a role in recovery from brain insults, which may be extended to include insult from lead exposure." (PMID 17431502, 2007). "A further notable finding is the apparent lack of an association between APOE genotype and dementia, confirmed in Kenya." (PMID 17659078, 2007). "Retinal Chlamydia pneumoniae load tightly tracks with matched cortical load and is enriched in APOE ε4 carriers and patients with higher Braak stage and worse cognitive status, thereby linking a retinal bacterial signature to widespread AD neuropathology and dementia severity." (PMID 41571675, 2026). "In addition, we found that the eGDR-dementia association was more pronounced among females and APOE ε4 noncarriers." (PMID 41181882, 2026). "In addition, APOE ɛ4 noncarriers with eGDR quartile 4 have the lowest dementia risk and the lowest BAG." (PMID 41181882, 2026). "Increased frailty in people who were cognitively unimpaired increased the risk of progression to mild cognitive impairment (MCI) and dementia, and in people who had MCI, increased frailty increased the risk of progression to dementia, independent of apolipoprotein E (APOE) ε4 carrier status." (PMID 41569280, 2026). "Genetic and experimental evidence also imply that the effects of variation in APOE on AD and all-cause dementia risk are highly unlikely to be due to nearby co-inherited genetic variation (in linkage disequilibrium with APOE), rather than the APOE variants per se9." (PMID 41522467, 2026).
dementia (continued). "Dementia cases (n = 614, of which 451 [73.5%] were incident) were recruited at an older age (median 71.3 versus 39.0), were more likely to be male (58.6% versus 44.5%), and were more likely to carry at least one APOE ε4 allele (26.4% versus 19.6%) than controls without dementia (n = 50 490)." (PMID 42205162, 2026). "In conclusion, our results point out to an oligogenic genetic architecture for delirium, with the APOE locus identified as a strong, potentially population-specific genetic risk factor, independently of dementia; however, further replication in larger non-European cohorts is required." (PMID 41286463, 2026). "Hence, this study aimed to examine the associations between comprehensive lifestyles and APOE e4 status—and their potential interactions—with multiple brain structural phenotypes among 24 912 participants without dementia from UK Biobank." (PMID 41140810, 2025). "Based on previous research, we investigated whether KL-VSHET would be associated with a lower likelihood of aMCI or dementia due to AD compared to controls in APOE ε4 carriers vs. non-carriers." (PMID 41163083, 2025). "Therefore, the purpose of this study was to examine whether the association between CMP and dementia is modified by the APOE genotype and to explore whether analgesics may mitigate the effect of CMP on dementia risk." (PMID 40101131, 2025). "Thus, APOE variants are currently proposed to be a risk factor for the progression of synucleinopathies with just LB pathology, like PD, to dementia, such as DLB or Parkinson's Disease Dementia (PDD)." (PMID 39996490, 2025). "This interaction between APOE genotype and physical activity may contribute to the variability in cognitive symptom onset and clinical outcomes in human APOE4 carriers, such that those who adhere to a more active lifestyle might delay or prevent the vascular dysfunction that precedes dementia." (PMID 39880935, 2025). "In addition, the finding of elevated levels of APOE, a well-recognized AD-associated protein, suggests that proteome changes outside HSA21 contribute throughout life to modulate the neuropathological phenotype most likely impinging on dementia onset." (PMID 41269384, 2025). "Recent studies showed that APOE ε4 modifies the protective associations of FOS with incident all-cause dementia and vascular dementia, suggesting that only noncarriers of APOE ε4 may benefit from FOS." (PMID 40949174, 2025). "Consistent with our second hypothesis, we found that greater cumulative social adversity was associated with higher dementia risk, regardless of APOE status." (PMID 41264567, 2025). "A previous study investigating the impact of both a healthy and a western-like dietary pattern in relation to all-cause dementia, found a risk reducing effect of a healthy dietary pattern among APOE ε4 non-carriers, and a risk increasing effect of a western dietary pattern among APOE ε4 carriers." (PMID 40222839, 2025). "Also in line with our Tex findings on amyloid, a recent study found that BBB permeability was associated with dementia, but not with amyloid pathology or APOE genotype." (PMID 41391236, 2025). "Other work showed that vascular risk factors did not increase dementia risk in APOE ε4 carriers." (PMID 40772428, 2025). "First, we assessed whether KL-VSHET was associated with a reduced likelihood of aMCI or dementia due to AD compared to being cognitively intact and whether this association was different in APOE ε4 carriers compared to non-carriers." (PMID 41163083, 2025). "•The EAT-Lancet diet reduced the risk of AD and dementia among APOE ε4 non-carriers." (PMID 40222839, 2025). "Specifically, men with SDB tended to show a higher likelihood of developing dementia compared to men without SDB, suggesting that sleep apnea may increase dementia risk, particularly in individuals without the ApoE ɛ4 allele." (PMID 40782185, 2025).
dementia (continued). "Participants who developed dementia were older, more likely to be female, less educated, diagnosed with more chronic diseases, and more likely to be apolipoprotein E allele ε4 (APOEε4) carriers than those who did not develop dementia during the follow-up period." (PMID 40140622, 2025). "The interaction with APOE but not dementia family history supports the hypothesis that other genetic or environmental risk factors are at play in the presence of the APOE ε4 allele, which require further study." (PMID 40476544, 2025). "In one report, low educational attainment was significantly associated with higher dementia risk only in APOE ε4 carriers, or in those at greater genetic risk for AD as indicated by their polygenic scores, and not in non-APOE ε4 carriers or those at lower genetic risk for AD." (PMID 40794236, 2025). "However, in support that microglial responses could be associated with APOE isoforms, it was observed that microglia stained for IBA1 were less ramified in patients with dementia, particularly in the hippocampus and superior and middle temporal gyrus." (PMID 39696753, 2025). "In addition to its function as a polymorphic protein, ApoE genes can be involved in many biological processes, which may contribute to the pathogenesis of dementia, particularly AD." (PMID 38803449, 2024). "Furthermore, the APOE loss-of-function R154S mutation (Christchurch) highlights the link between tau pathology and APOE genotype, as the patient displayed excessive levels of amyloid pathology, but very low levels of tau and as a result only developed mild dementia late in life." (PMID 39524360, 2024). "Besides, APOE ε4 carriers have higher Aβ plague burden and more severe neurofibrillary tau tangles than APOE ε4 non‐carriers, which indicates higher risks of progressing to dementia." (PMID 38421124, 2024). "We had hoped that this study would shed new light on possible mechanisms by which PTSD confers risk for dementia but hypotheses for our primary variables of interest, APOE ε4, PTSD (and their interaction) were not supported." (PMID 38431614, 2024). "As expected, development of MCI or dementia was significantly negatively correlated with scores across each cognitive domain and more negative slopes were associated with APOE Ɛ4 genotype." (PMID 39055623, 2024). "Based on the same database, another recent study indicated that affective dysregulation among non-demented individuals was associated with an increased risk of incident dementia, compared to no NPSs, and this relationship was stronger among APOE e4 non-carriers." (PMID 38473892, 2024). "Interestingly, deficits in attention, specifically the shifting of visuospatial attention, have been found in APOE −e4 allele carriers who do not have dementia." (PMID 39632090, 2024). "Nonetheless, previous reports of strong associations between frailty and incident dementia even after adjusting for social deprivation (e.g. Townsend deprivation index) 8, and within both APOE ε4 carriers and non-carriers 13, lead us to maintain confidence in our findings." (PMID 38746437, 2024). "Similarly, genetic risk for dementia, often approximated using APOE ε4 status, was not adjusted for." (PMID 38746437, 2024). "Finally, it was not possible to control for other confounding variables that may influence dementia development, such as APOE genotype or imaging biomarkers, in this study." (PMID 38974906, 2024). "100% of models that included APOE e4/e4 (ORs = 1.56–8.76), 100% of models that included TBI (ORs = 3.42–14.48), 97% of models with hypertension (ORs = 0.97–4.54), and 93% depression outputs (ORs = 0.87–3.36) are positively associated (OR > 1) with dementia outcomes." (PMID 38807092, 2024). "However, neither the total CSF APOE concentration nor any specific isoforms have been associated with the Aβ accumulation or the severity of dementia in patients with AD." (PMID 39449522, 2024).
dementia (continued). "Moreover, our findings suggest that dementia experts may be more hesitant to conduct APOE testing compared to their counterparts, inferred from the lower proportion of specialists versus non-specialists and the general clinician demographic in Japan." (PMID 38225507, 2024). "As an example, APOE ε4 homozygosity confers a > 90% lifetime risk of developing Alzheimer’s —MS has no genetic variation with such a potent effect on disease risk—yet no one argues that APOE ε4 causes Alzheimer’s, only that it strongly modulates the complex processes leading to dementia." (PMID 39161786, 2024). "CAIDE 2, which incorporates age and APOE ε4 status, and ANU–ADRI, which weights age very highly in its scoring, generally performed better than CAIDE 1 and LIBRA, indicating that age and genetic status were likely stronger predictors of dementia risk than lifestyle factors." (PMID 39023302, 2024). "Additionally, those in the low ADI group were more likely to be diagnosed with AD or some other form of dementia (97.4.1% vs. 90.7% in the high ADI group) but were similar on other clinical categories including Braak Stage, CERAD, ABC score, and APOE ε4 alleles." (PMID 38663907, 2024). "These APOE alleles are also linked, to a lesser extent, with global cognition and specific cognitive domains including episodic memory, executive function, and verbal fluency in individuals without dementia." (PMID 38889280, 2024). "Psychotic features may be more strongly related to dementia risk among APOE e4 carriers compared to non-carriers." (PMID 38473892, 2024). "Specifically, the ApoE proteins are responsible for lipid transport and cholesterol homeostasis within the central nervous system, and ApoE knock-out is associated with Tau and Amyloid beta (Aβ) aggregation, microglia activation, BBB disruption, and accelerated symptoms of dementia." (PMID 38899254, 2024). "Similarly, findings relating circulating apoE4 to cardiovascular risk (i.e., another risk factor for dementia) are not conclusive, probably due to heterogeneous bindings between apoE and circulating lipids and lipoproteins." (PMID 39234633, 2024). "This review highlights the novel role of the Pin1-cis P-tau axis, and to a lesser extent ApoE, in the development of preeclampsia and propagation of cis P-tau-mediated tauopathy from the placenta to cerebral tissues in the long term, leading to dementia similar to other neurodegenerative conditions." (PMID 39857613, 2024). "This framework interprets the modifiability of MDRFs from the perspective of an individual seeking to reduce their dementia risk and considers non-modifiable dementia risk factors, such as older age, the APOE ε4 allele and sex, as a basis for comparison or contextualization of MDRFs." (PMID 38230714, 2024). "But at least two case-control studies have explored the relationship between CST3 polymorphism and APOE-ε4 allele in Alzheimer’s patients of European ancestry, one concluding a synergistic association between APOE-ε4 allele and CST3 polymorphism on dementia risk." (PMID 37323925, 2023). "However, the multiplicative interaction between APOE ɛ4 and BMI change on dementia risk was not statistically significant (p for interaction = .710)." (PMID 35921193, 2023). "Our study also suggested that higher Vitamin D levels might be particularly beneficial for dementia among APOE e4 genotype carries in women, while in men, higher vitamin D levels appeared to benefit both APOE ε4 carriers and non-carriers, but the effect was greater in non-carriers." (PMID 37246226, 2023). "In the current study, the lack of significant multiplicative interaction between BMI change and APOE genotypes indicated that the strength of associations between BMI change and dementia might not differ by APOE genotypes." (PMID 35921193, 2023). "However, wheather vitamin D and grip strength may jointly modify the effect of APOE genotype on dementia remain largely unknown." (PMID 37246226, 2023).
dementia (continued). "In women, participants who had highest tertile of vitamin D was associated with lower risk of dementia compared to those with lowest tertile of vitamin D among APOE e4 carries (HR = 0.73; 95% CI 0.63–0.85), but not among APOE e4 non-carries (HR = 0.91; 95% CI 076–1.08)." (PMID 37246226, 2023). "Finally, further research is needed to clarify if APOE is an independent driver of dementia in LBD." (PMID 37987016, 2023). "Thus, we hypothesize that if an effect of the APOE ε4 status has to be sustained, this has to be driven through the impact of the AT(N) profiles on conversion to dementia." (PMID 36674881, 2023). "Furthermore, the associations were much stronger amongst participants with a lower genetic risk of dementia based on APOE status, but non-APOE PRS did not modify the associations." (PMID 37605228, 2023). "However, clinical dementia services do not consistently provide genotyping or testing for purported common dementia risk polymorphisms (e.g., Apolipoprotein E [APOE])." (PMID 36829050, 2023). "However, the risk was 30% lower in the AFR compared to EUR groups, consistent with prior studies that observed differential risk between APOE alleles and dementia in non-EUR compared to EUR populations." (PMID 37425708, 2023). "This and other factors identified in this review may influence the relationship (exposure proximity, awareness of APOE status, dementia worry, and sensitivity of measures) and should inform future studies examining moderators of these relationships or differential effects across subgroups." (PMID 37497342, 2023). "One hundred ninety-two early-stage dementia (including mild cognitive impairment and mild dementia) and 259 cognitively unimpaired participants from a neurocognitive research cohort with neuroimaging data, APOE genotyping, and neuropsychological assessments were studied." (PMID 37270543, 2023). "The use of polygenic risk scores which exclude the APOE region (to determine the contribution of non-APOE genes) combined with APOE status may provide the best strategy to identify individuals at increased risk of dementia." (PMID 37833762, 2023). "The risk of dementia with large bodyweight change may be higher for APOE ɛ4 carriers than noncarriers." (PMID 35921193, 2023). "Furthermore, some studies did not adjust for ApoE status, which does not reflect its potential to modify the association between obesity and dementia risk." (PMID 38137454, 2023). "While associations between serum immunoglobulins and early markers of dementia could not be established in this population-based sample, it may be valuable to consider factors such as APOE-ε4 allele carriership and sex in future investigations." (PMID 37936180, 2023). "However, the study covariates were chosen based on conditions that were previously found to be associated with ADHD and dementia (ie, met the definition of a confounder [unlike APOE ε4, which has not been associated with ADHD risk])." (PMID 37847497, 2023). "Thus, this study aims to draw full trajectory maps of cerebral gray matter atrophy in the elderly with and without APOE ε4 variant from the normal cognition stage to dementia." (PMID 37323144, 2023). "The presence of preclinical dementia may account for observed associations between APOE e4 and cognitive function leading to an overestimation of the effect of APOE e4 in age-associated, non-pathological cognitive decline." (PMID 36481934, 2023). "Indeed, according to the notion of stochastic risk or protective factors and although it is known that APOE ε4/ε4-carriers developed dementia about 10 years earlier than APOE ε2 carriers, there was still significant discrepancy in the age of onset for APOE ε4/ε4-carriers." (PMID 38132357, 2023).